CTLA4 (cytotoxic T-lymphocyte associated protein 4)
Diseases named in the same sentence as CTLA4 in open-access papers (continued):
Sharing a sentence is not in itself a finding about the gene and the disease.
tumor (continued). "Overall, there is reliable evidence supporting a greater efficacy of the combined PD-1/CTLA-4 blockade over the two monotherapies in reversing tumor immune inhibition." (PMID 33935977, 2021). "By contrast, when IRE and anti-CTLA-4 primary therapy was followed up by secondary therapy with anti-PD-1, the average tumor growth was held in check resulting in tumor sizes significantly smaller than the endpoint values of sham-treated tumors." (PMID 34162858, 2021). "This is a consequence of the actions of multiple inhibitory receptors including PD1 and CTLA-4 that are induced by chronic antigenic stimulation or inhibitory receptor ligands expressed by tumor cells." (PMID 34926643, 2021). "Anti-tumour effects of CTLA-4 blockade have been found to depend on distinct Bacteriodes species both in mice and human models, particularly B. thetaiotaomicron and B. fragilis being associated with efficacious CTLA-4 blockade." (PMID 36046753, 2021). "The successful application of anti-PD-1 and anti-CTLA-4 antibodies in tumor therapy provides a promising opportunity for tumor immunotherapy." (PMID 34659197, 2021). "In our study, we demonstrate that IRE in combination with anti-CTLA-4 boosts endogenous TRM formation in numerous NLT, and is associated with protection from recurrent tumor challenge." (PMID 34162858, 2021). "A high immunohistochemical (IHC) staining of PD-L1 tumor expression and/or PD-1 and CTLA-4 TILs expression on biopsy specimens is the first fundamental step for treatment selection, being generally but not only related to higher response rate to ICI therapy." (PMID 33920423, 2021). "Early-stage clinical trials testing the second-generation DNMTi guadecitabine with ipilimumab (anti-CTLA-4) in metastatic melanoma patients showed promising tumor immunomodulatory and clinical activities." (PMID 34001289, 2021). "Thirdly, while PD1/PD-L1 and CTLA4 are important immune checkpoints, the immunosuppressive adenosine molecule in the tumour stroma represents an emerging therapeutic target." (PMID 34740105, 2021). "Therapeutically, when CTLA-4 on T cells is blocked with a targeted antibody, there is an increase in overall T cell proliferation and an increased probability of forming a tumor-specific immune response." (PMID 34136405, 2021). "Nivolumab (anti-PD-1), atezolizumab (anti-PD-L1), and tremelimumab (anti- CTLA4), have been proved to be safe and have effective anti-tumor responses for treating HCC." (PMID 34975896, 2021). "Combining the MD5-1 mAb and anti-CTLA4 to treat mice increases the sensitivity of tumors to anti-CTLA4 and significantly delays tumor progression." (PMID 34403220, 2021). "The primary activity of the CTLA-4 pathway is the draining of the lymph nodes, where naïve T-cells are primed by exposure to tumor antigens (presented by APCs) and become activated." (PMID 34683167, 2021). "The authors observed increased tumor size regression and improved mice survival when anti-CTLA-4 was encapsulated into liposomes with respect to free Ab." (PMID 33800368, 2021). "Normally, CTLA-4 suppresses T cells in the early stages of the immune cycle in lymph nodes, while PD-1 regulates the immune response in peripheral tissues or tumor sites 37,38." (PMID 33391454, 2021). "Lastly, TAMs can suppress the function of tumor-infiltrating lymphocytes (TILs) by expressing the ligands of the inhibitory receptors PD-1 and CTLA-4." (PMID 34771482, 2021). "During tumor progression, cancer cells can avoid this effect by overexpression of programmed death ligand 1 (PD-L1) and cytotoxic T-lymphocyte antigen 4 (CTLA-4) (compare corresponding subchapter)." (PMID 33562138, 2021). "We observed that FLT3L monotherapy caused expansion of pDC and Tregs in tumor-draining lymph nodes, which was further enhanced when FLT3L was combined with XRT or dual CTLA-4/PD-1 blockade." (PMID 34083417, 2021).
tumor (continued). "Further studies showed that in the internal environment of SD, CTLA-4 promoted tumor invasion and metastasis by regulating the PTEN/CD44 pathway." (PMID 34744733, 2021). "As important tumor antigens for the human immune system, neoantigens have emerged from studies of novel ICIs targeting CTLA4 and PD1, which are expressed by activated T cells." (PMID 34531875, 2021). "Mice that received BEMPEG and anti-CTLA-4 treatments or PBS were euthanized at earlier time points due to primary tumor size." (PMID 33937052, 2021). "Immunotherapies based on the use of immune checkpoint inhibitors (ICI) target T-cell co-inhibitory signalings, namely, CTLA-4 and PD-1/PD-L1, and hence relieve their suppression of anti-tumor T-cell activity and prevent tumor immune evasion." (PMID 34026830, 2021). "Accordingly, we harvested subcutaneous tumours from mice treated with anti-PD-1, anti-CTLA-4, both anti-PD-1 and anti-CTLA-4 or relevant isotype controls, and we assessed immune infiltrates by flow cytometry." (PMID 34784792, 2021). "Tregs expressing CTLA-4 play a crucial role in the maintenance of immunological self-tolerance and homeostasis and suppressing the anti-tumor immune response." (PMID 33758613, 2021). "It is well known that tumor cells are able to upregulate the expression of checkpoint molecules (such as CTLA-4, PD-L1, and PD-1), leading to anergy of cytotoxic T cells in the tumor microenvironment." (PMID 34830221, 2021). "In particular, low-dose peri-tumoral injection of anti-CTLA-4 mAb was as effective in controlling tumor growth as the other systemic routes, and the efficacy of the local administration was enhanced by Tregs reduction." (PMID 33530329, 2021). "Cancer immunotherapies with ICIs, such as agents targeting PD-L1, PD-1, or CTLA4, help the immune system to recognize and attack tumor cells." (PMID 33753855, 2021). "In mouse models of HCC, IDO1 blockade along with anti-CTLA-4 treatment proved a more effective means to reduce tumor growth than anti-CTLA-4 monotherapy, paving the way for IDO1 inhibitors to be tested in combination therapies." (PMID 34440865, 2021). "Antibodies targeting the PD-1, PD-L1, and CTLA-4 immune checkpoint axis have been used in a variety of tumor types." (PMID 34462476, 2021). "Antibody blockade of PD-1 was shown to enhance T cell anti-tumor response, supporting its rational for cancer immunotherapy, but with milder adverse events (AEs) than CTLA-4 blockade." (PMID 36046145, 2021). "Since the combination of anti-PD-1 and anti-CTLA-4 antibody treatment has been shown to be more effective than anti-PD-1 alone treatment in the RENCA tumor model, we combined both anti-CTLA-4 and anti-PD-1 antibodies with the vaccine." (PMID 34862254, 2021). "A recent report shows that blockade of PD-L1 plus CTLA-4 is able to inhibit tumor growth of B16 melanoma in a mice model through the induction of ferroptosis." (PMID 34742351, 2021). "The rationale of anti-CTLA-4 antibody therapy is that it enhances immune responses against tumor by enhancing tumor-specific effector T-cell response." (PMID 34006227, 2021). "On the other hand, rich expression of IFN-γ, CXCL9, and CXCL10 and significantly high CTLA-4 or PD-1+ CD8/CD4 T cells were observed in the tumor microenvironment of CMS 1 patients." (PMID 33968712, 2021). "A few recent studies suggest that anti-CTLA-4 mAbs play a major role in regulating the function of tumor infiltrating Tregs." (PMID 34806028, 2021). "Administration with the 11-bacterium mix (11-mix) recovered efficacy of anti-PD1 or anti-CTLA4 with infiltration with IFNγ+ T cells in MC38 tumor." (PMID 34589427, 2021). "As we know, immune checkpoint inhibitors are great innovations in tumor therapy in the past decade, in which PD-L1, PD-1, and CTLA4 are the most widely studied checkpoints." (PMID 34539785, 2021).
tumor (continued). "Sema4D mAb in combination with either CTLA-4 or PD-1 blockade enhanced rejection of tumors or tumor growth delay, resulting in prolonged survival with either treatment." (PMID 35003065, 2021). "Varying degrees of clinical responses to ICI treatments, including anti-PD-L1, anti-PD-1 or anti-CTLA-4, have been noted in different tumor types." (PMID 34069452, 2021). "Immune checkpoints, mainly including PD-1/PD-L1 and CTLA-4, play a key role in the initiation and preservation of tumor immune escape." (PMID 34899747, 2021). "We found that anti-CTLA4 antibody alone significantly reduced tumor growth as measured by tumor growth kinetics, AUC or tumor weight at the end of the experiment." (PMID 34692697, 2021). "Esmaily and co-authors silenced CTLA-4 in tumor-infiltrating T cells by siRNA-loaded chitosan–lactate, which resulted in tumor regression and increased mice survival." (PMID 35008249, 2021). "In 2015, landmark pre-clinical mouse studies confirmed that the anti-tumor effects of CTLA-4 and PD-L1 blockade were facilitated by commensal intestinal flora." (PMID 34305883, 2021). "For this reason, blockade of the CTLA-4 can be an effective strategy to enhance the number of activated CD8-positive T cells that infiltrate the tumor cells." (PMID 34956912, 2021). "On the other hand, serum butyrate levels limit the anti-tumor efficacy of anti-CTLA4 therapy in metastatic melanoma by restraining the up-regulation of CD80/CD86 on dendritic cells and ICOS on T cells, accumulation of tumor-specific T cells and memory T cells." (PMID 33708214, 2021). "The use of anti-PD-1 therapy counteracts the inhibitory function of 4PD1hi cells and improves anti-tumor activity when used in combination with CTLA-4 blockade." (PMID 33864502, 2021). "The highly increased Th1 cells probably contributed to the anti-tumor effect of CTLA-4 blockade in TC-1/dCD80-1-induced tumors." (PMID 33923750, 2021). "Still, further studies on CTLA-4 expression in veterinary neoplastic diseases are necessary as currently available data are still few." (PMID 34359249, 2021). "In patients with CRC, the production of immune checkpoints, such as PD-L1 and CTLA-4 incite an anti-tumour immune response by allowing tumour cells to escape T-cell detection." (PMID 34272358, 2021). "The co-delivery of tumor anti-CTLA-4, anti-PD-1, and tumor vaccines using injectable PEG-b-poly(L-alanine) hydrogels increased the efficacy of immunotherapy by reducing the number of Tregs and increasing the number of activated CD8+ T cells in the TME." (PMID 35111169, 2021). "Conversely, expression of the genes associated with NK cell exhaustion, such as PDCD1, CTLA4, KLRC1, NR4A1, and SOCS3, was upregulated in tumor-infiltrating NK cells." (PMID 34535671, 2021). "Tumor cells and TILs express immunosuppressive regulators, such as PD-1, PD-L1, and CTLA4, thereby allowing tumor growth and progression." (PMID 34063828, 2021). "The tumour cells can escape from the killing of T cells by activation of PD‐1/PD‐L1, CTLA4/CD80/CD86 and other immune checkpoints." (PMID 33325636, 2021). "Due to CTLA4 upregulation on tumor–infiltrating CD8+ T cells, a CTLA4‐targeting aptamer STAT3 siRNA chimera was created that triggers CD8+ T cell reactivation in the tumor microenvironment." (PMID 34532286, 2021). "PD-1, PD-L1 and CTLA-4 are known biomarkers for tumor immunity and have won general recognition in immunotherapy." (PMID 33819918, 2021). "An enhanced therapeutic effect of F8-IL2 (an antibody-IL2 fusion protein) bombinated with anti-PD-1, anti-PD-L1 and anti-CTLA-4 antibodies was observed in immunocompetent mice bearing CT26 tumours." (PMID 33763344, 2021). "The same study also highlighted an inverse correlation between CTLA4 promoter methylation and the presence of tumor-infiltrating lymphocytes (TILs), which play a critical role in tumor control and response to immunotherapy." (PMID 34575678, 2021).
tumor (continued). "These antibodies are perceived to mediate anti-tumor activity by blocking CTLA-4 or PD-1/PD-L1 signaling pathways, releasing the suppression on effector cells." (PMID 34321536, 2021). "Further, anti-CTLA4 therapy-mediated tumour vascular normalisation was accompanied by a striking escalated infiltration of eosinophils into tumours, which was dependent on T lymphocytes and IFN-γ production." (PMID 33917287, 2021). "By contrast, mice that had previously achieved complete remission following dual IRE + anti-CTLA-4 therapy were 100% protected from secondary tumor challenge, and showed significant survival advantage over mice not receiving IRE therapy (9/9 mice)." (PMID 34162858, 2021). "As a well-studied immune checkpoint protein, CTLA-4 plays a crucial role in the tumor immunoreaction process." (PMID 31911758, 2020). "Inflamed TIMEs, or “hot” tumor, are characterized by the abundant accumulation in the tumor core and the stroma of T cells expressing PD-1 and/or CTLA-4, myeloid cells and monocytes." (PMID 33680911, 2020). "Nanovaccine with tumor antigen MUC1 mRNA designed against triple negative breast cancer in combination with an anti-CTLA-4 monoclonal antibody can be successfully delivered to DCs in lymph nodes resulting in an enhanced T cell anti-tumor immune response." (PMID 32792853, 2020). "Immunostaining analysis revealed that from the 49 tumor specimens evaluated, 34 (81%) showed a CTLA-4 positive expression in interstitial lymphocytes and 2 (4%) in tumor cells." (PMID 32123292, 2020). "In particular, cytokine-activated STAT3 can promote cancer proliferation and invasion while suppressing anti-tumor immunity by regulating the expression of immune checkpoint proteins PD-1, PD-L1 and CTLA4." (PMID 33216733, 2020). "The most widely used immune checkpoint blockade (ICB) therapeutic strategies target the PD-1/PD-L1 and CTLA4 axes to regulate anti-tumor immune activity with demonstrated clinical benefits." (PMID 31968651, 2020). "In HNSCC, high levels of TAMs in the tumor micro-environment are correlated with poor prognosis, because of the CTLA-4-mediated immunosuppression and the expression of immunosuppressive cytokines and PD-L1." (PMID 32344813, 2020). "Monoclonal antibodies impeding the PD-1/PD-L1 binding and affecting the CTLA-4 axis are able to restore tumor T cell recognition and tumor regression in a relevant subset of terminally ill patients." (PMID 33013822, 2020). "We found that PD-1, LAG-3 and Tim-3 were the three most upregulated checkpoint receptors on non-Treg CD4+ and CD8+ TILs as compared to autologous peripheral T cells, whereas PD-1, CTLA-4 and LAG-3 were dominant on tumor-associated Tregs." (PMID 32582215, 2020). "This immunosuppressive mechanism in tumor environments can be counteracted by anti-CTLA-4-antibodies." (PMID 33374927, 2020). "More T-cells were detected at the invasive margins and toward the tumor core in tumors treated with combined anti-CTLA-4 and anti-PD-L1 therapy." (PMID 32793206, 2020). "Immunohistochemistry analysis also showed positive CTLA-4 immunostaining in lymphocytes of samples presenting tumor-infiltrating lymphocytes (TILs)." (PMID 32850353, 2020). "The checkpoint-blockade approach, which involves monoclonal antibodies targeting PD-1/PDL1 and CTLA4, and adoptive cell transfer of tumour-infiltrating lymphocytes (TILs) or CAR T cells are two front-line T-cell-based immunotherapies." (PMID 32694789, 2020). "It was established that tumor cells can escape through immune checkpoint pathways including CTLA-4 and PD-1 in hematological malignancies." (PMID 33150182, 2020). "Another proposed combination therapy is to join PD1/PDL1 blocking (or coblocking with anti-CTLA4 therapy) with dexosome vaccine, which results in the suppression of tumor-infiltrating lymphocytes and T cell activation." (PMID 33228747, 2020).
tumor (continued). "To test selectivity of the anti-CTLA-4 antibodies, we treated tumor bearing mice with anti- CTLA-4 antibodies, including pH-sensitive HL32 and pH-insensitive Ipilimumab." (PMID 31991588, 2020). "Radiotherapy combined with immune checkpoint inhibition of CTLA-4 effectively inhibited tumor growth, increased the overall survival of CT26 tumor-bearing mice, and [64Cu]NOTA-CD8a PET identified the responding mice before tumor growth inhibition was evident." (PMID 32086762, 2020). "To define the crosstalk between the activated-CTLA-4 axis in tumor cells and the intra-tumor immune infiltrate, we estimated the immune cellular composition of the analyzed TNBC tumors based on their transcriptome profiles, through dedicated algorithms." (PMID 32850353, 2020). "Addition of anti-RL did not improve the response to anti-CTLA4 (or anti-PD-L1) in RANK−/− tumors as did in RANK+/+ tumors, suggesting that the augmented benefit of the anti-RL/anti-CTLA4 combination was driven by inhibition of RANK signaling in tumor cells." (PMID 33303745, 2020). "Compared with peripheral Tregs, inhibitory receptors PD-1, CTLA-4, and Tim-3 were significantly increased in tumor-infiltrated Tregs in HNSCC, signifying more suppressive function." (PMID 33072064, 2020). "Collectively, our data indicate that combination of IL36 and CTLA-4 mAbs is a more effective immunotherapy for tumor than individual treatment with IL36 or CTLA-4 mAbs." (PMID 32351508, 2020). "Preclinical studies in mouse tumor models have supported the molecular design of PD-1 and CTLA4 antibodies that are approved for clinical use." (PMID 33127658, 2020). "The higher NR2F6 expression in these lymphocytes correlated with a higher PD-1 and CTLA-4 expression in the lymphocytes, as well as PD-L1 expression in tumor cells." (PMID 32752295, 2020). "Ipilimumab is a monoclonal antibody, which antagonizes CTLA-4 and selectively depletes T-regs in the tumor microenvironment, stimulating an anti-tumor immune response." (PMID 32443455, 2020). "In cancer, the development of an antibody to block the CTLA-4 to B7-1/B7-2 ligation leads to potent anti-tumor responses." (PMID 33182298, 2020). "The numbers of infiltrating FoxP3+ T-cells and CTLA-4+ cells in tumor stroma were greater than those in tumor parenchyma." (PMID 32785290, 2020). "Following the ILP procedure, tumour‐bearing animals received an intraperitoneal injection of anti‐CTLA‐4 antibody, anti‐PD‐1 antibody or an isotype control, at day 8, 10 and 12 post‐implantation." (PMID 32419365, 2020). "Immunotherapy is the Hope of Advanced Tumor, Phase I clinical trials showed that response rates to CTLA4 and PD-L1 Immunological checkpoint inhibitors were 17.6% and 20%." (PMID 31988807, 2020). "siRNA-mediated knockdown of CTLA-4 in a DC vaccine significantly improved tumor control and survival, correlating with vastly increased frequency of activated CD8+ T-cells." (PMID 33384695, 2020). "Despite the comparable number of CD4+ T cells in inflammatory infiltration in normal and tumor tissues, a higher co-expression of PD-1 and CTLA-4 has been found in the T lymphocyte pool present in tumor tissues compared to control tissues." (PMID 32488850, 2020). "We further delineated the effects of SB-3CT and anti-CTLA-4 treatment in combination or alone on the tumor–immune microenvironment." (PMID 32988398, 2020). "Checkpoint blockade of CTLA-4 supports induction phase while PD-1/PD-L1 blockade maintains effector phase of anti-tumor cell responses." (PMID 33329567, 2020). "When the TERT DNA vaccine was combined with either PD-1 or CTLA-4 blockade, tumor growth was significantly slowed compared to the control." (PMID 33008010, 2020). "Whilst characterised by low frequency of anti-tumour responses, single-agent anti-CTLA-4 therapy leads to long-term survivorship in ~20% of patients, providing evidence of long-lasting immune reconstitution." (PMID 32157213, 2020).